TNF (tumor necrosis factor)
Diseases named in the same sentence as TNF in open-access papers (continued):
Sharing a sentence is not in itself a finding about the gene and the disease.
Insulin resistance (continued). "In 3T3-L1 adipocytes, insulin resistance induced by chronic inflammation (chronic Tumour Necrosis Factor-alpha incubation, TNF) or hyperinsulinemia (chronic insulin incubation, CI) was sufficient to cause a marked downregulation of mitochondrial proteins." (PMID 38960128, 2024). "TNF-α is a marker of insulin resistance in pregnancy, and our findings indicate that insulin resistance is not affected in the longer term in GDM pregnancies." (PMID 39696496, 2024). "Increased inflammatory cytokines levels released by adipose tissue, including TNF-α and IL-6, promote insulin resistance and correlate with the progression of diabetic nephropathy (DN)." (PMID 38510054, 2024). "Secondly, it induces insulin resistance by activating NF-κB and upregulating inflammatory factors such as TNF-α and IL-6." (PMID 40302954, 2024). "Inflammatory cytokines released by hepatic adipose tissue, such as tumor necrosis factor-alpha (TNF-α) and interleukin-6 (IL-6), can impair insulin signaling pathways, leading to insulin resistance." (PMID 39683601, 2024). "These 170 action targets were mainly enriched in insulin resistance, inflammation, and metabolism, such as TNF pathway, MAPK pathway, and PI3K-Akt pathway." (PMID 39285464, 2024). "Specific future focus should be maintained not only on suppression of TNF-α signaling as a critical target in the onset of insulin resistance, but also on the putative protective roles of the COX-2-mediated or IL-17A-mediated pathways in metabolic disorders." (PMID 38672413, 2024). "Pro-inflammatory markers, such as tumor necrosis factor α (TNF-α), interleukin-6 (IL-6), interleukin-1β (IL-1β), and leptin, demonstrate a positive correlation with insulin resistance and the characteristics of MetS." (PMID 38671898, 2024). "This modulation regulates pathways involved in upregulating the expression of pro-inflammatory genes (IL-6, TNF-α, monocyte chemoattractant protein-1), linking metabolic disorders such as insulin resistance, glucose homeostasis, and inflammatory response." (PMID 38638434, 2024). "Oxidative stress is related to metabolic syndrome and, by the activation of NF-KB, induces the transcription of TNF-α and creates an inflammatory environment, a triggering factor for insulin resistance and hyperandrogenism." (PMID 39336541, 2024). "TNF-α is a crucial pro-inflammatory agent that greatly contributes to the onset of insulin resistance and the development of T2DM." (PMID 39328924, 2024). "In consequence, we found that the top five pathways were IL-17 signaling pathway, TNF signaling pathway, Non-alcoholic fatty liver disease, NF-kappa B signaling pathway, and Insulin resistance, respectively." (PMID 39005933, 2024). "Tumor necrosis factor-α (TNF-α) serves as an immunomodulatory factor in the pro-inflammatory response and is significantly linked to the onset of insulin resistance." (PMID 39845797, 2024). "The pro-inflammatory cytokine, TNF-α, frequently assumes a pivotal role in the pathogenesis of hepatic steatosis and insulin resistance (IR), thereby impeding insulin secretion and impairing β-cell function." (PMID 38254542, 2024). "Two well-known milk protein-derived peptides, IPP and VPP, demonstrated effective enhancement of insulin signals and anti-inflammation via the NF-κB pathway under TNF stimulation and prevention of insulin resistance." (PMID 38672494, 2024). "Experiments were conducted to assess the effect of vanadium complexes on radiolabeled glucose uptake to hepatocytes, in which insulin resistance was induced by the pro-inflammatory factor TNF and hyperlipidemia." (PMID 38399444, 2024). "By investigating the impact of CXCR1/2 inhibition on TNF-α induced insulin resistance, this study seeks to provide insights into the potential therapeutic targeting of chemokine receptors to improve insulin sensitivity." (PMID 39627194, 2024).
Insulin resistance (continued). "These vesicles often carry inflammatory cytokines like IL-6 and TNF-α, which interfere with insulin signaling pathways, contributing to insulin resistance." (PMID 39796048, 2024). "SIRT1 also alleviates tumor necrosis factor-α (TNF-α)-induced insulin resistance partly through the anti-inflammatory effects of 3T3-L1 adipocytes." (PMID 39372420, 2024). "Tumor necrosis factor α (TNF-α) has also been linked to endothelial dysfunction, increased atherogenic risk, development of insulin resistance and diabetes." (PMID 39176098, 2024). "According to previous studies, fatty liver affects gastric carcinogenesis through enhanced insulin resistance; chronic inflammation with various signaling pathways, such as IL-6 and TNFα; adipocytokines; or alteration of gut microbiota." (PMID 38804394, 2024). "These senescent cells secrete senescence-associated secretory phenotypes (SASPs), such as activin A, IL-6 and TNF-alpha, that induce insulin resistance." (PMID 38937415, 2024). "Emphasizing the significance, the integration of TNF-α treatment with the 3D culture approach proved crucial, rendering our model more relevant and robust in elucidating the functional outcomes of insulin resistance in vitro." (PMID 38820505, 2024). "Highly metabolically active visceral fat generates several pro-inflammatory adipokines, such as resistin, TNF-α, and IL-6, contributing to systemic inflammation, insulin resistance, and the onset of metabolic disorders." (PMID 39335642, 2024). "Activated NF-κB upregulates the expression of various inflammatory cytokines (TNFα, IL-1β, IL-6) and influences insulin resistance." (PMID 38672494, 2024). "As FLLE and FLRE showed anti-insulin resistance induced by TNF-α in adipocytes, the anti-inflammation ability of the extracts was further investigated in macrophages." (PMID 38543073, 2024). "It is known that insulin resistance of skeletal muscle is induced in T2D via increased ROS and inflammatory cytokines (IL-6, TNFα, etc.)." (PMID 38392186, 2024). "Pro-inflammatory cytokines such as tumor necrosis factor (TNF)-α contribute to insulin resistance by inhibiting the insulin receptor tyrosine kinase activity and downregulating cellular glucose transporter genes." (PMID 38787165, 2024). "High-fructose diet (HFD) feeding and crocetin treatment in male Wistar rats reduced free fatty acid, rectified dysregulation of mRNA expression of adiponectin, TNF-α, and leptin which was probably related to alleviated insulin resistance." (PMID 38419885, 2024). "Inflammatory factors such as TNF-α trigger insulin resistance (IR), further complicating glucose metabolism in GDM patients." (PMID 38694942, 2024). "Cytokines produced by these cells, such as TNF, IFNγ and IL-1β, reach the bloodstream and contribute to the development of systemic insulin resistance (IR)." (PMID 39107476, 2024). "Inflammation-induced insulin resistance in the nervous system predominantly occurs due to increased levels of inflammatory factors such as ROS, endoplasmic reticulum stress, TNF-α/TNFR1, PKCs, and LPS/TLRs activation of intracellular JNK and IKKβ/NF-κB." (PMID 38818523, 2024). "Pioglitazone exhibits various anti-inflammatory activities, including the significant reduction of IL-6 and tumor necrosis factor α in individuals with insulin resistance." (PMID 38932215, 2024). "The genes that were attributed to significant KEGG pathways, including apoptosis, insulin resistance, TNF, NFKB, pancreatic cancer, and MAPK, were distributed among different miRNAs." (PMID 39022651, 2024). "Hepatic insulin resistance was observed with the elevated level of tumor necrosis factor-α (TNFα) via decreasing the insulin signaling and glucose transporter type 4 (GLUT4) expression." (PMID 38338579, 2024). "TNF-α is overexpressed in and secreted by adipose tissue of obese animals and humans, and its levels correlate to the degree of adiposity and insulin resistance." (PMID 38504163, 2024).
Insulin resistance (continued). "The activation of inflammatory pathways, as evidenced by elevated levels of TNF-α and other cytokines, further contributes to the vicious cycle of insulin resistance and oxidative stress." (PMID 39229375, 2024). "Excess NADPH induces oxidative stress and inflammatory responses by promoting the secretion of pro-inflammatory cytokines, such as TNF-α and interleukin 1β, and leads to severe insulin resistance in various tissues." (PMID 39330490, 2024). "Chronic inflammation marked by elevated IL-6 disrupts systemic metabolism, activating other pro-inflammatory cytokines like TNF-α and IL-1, creating a feedback loop that intensifies inflammation and insulin resistance." (PMID 39857603, 2024). "TNF-α is also one of the most important inflammatory mediators that correlates with insulin resistance and is critically involved in T2DM pathogenesis." (PMID 37991535, 2024). "Research has shown that the activation of PPARγ can reduce the transfer of fatty acids to the liver, decrease insulin resistance, and inhibit the expression of IL-6 and TNF-α." (PMID 39064674, 2024). "In this context, we utilized a TNF-α-based cellular model to induce insulin resistance (IR) due to its established role as a pro-inflammatory cytokine that disrupts insulin signaling." (PMID 39627194, 2024). "PPARs help reduce the expression of pro-inflammatory cytokines, such as interleukin (IL)-1, IL-6, and tumor necrosis factor (TNF)-α, which are involved in insulin resistance." (PMID 39519484, 2024). "Inflammatory mediators released from the liver and adipose tissue, such as TNF-alpha and IL-6, further exacerbate insulin resistance and create a pro-inflammatory environment that fuels both NAFLD and T2DM." (PMID 39617908, 2024). "High glucose conditions and exposure to TNF-alpha, which is known to play a crucial role in inducing insulin resistance and T2DM, are strong inducers of endothelial CTRP13 expression in vitro." (PMID 39120321, 2024). "Previous studies have shown a positive correlation between kallistatin levels and both TNF-α and carotid intima-media thickness in patients with insulin resistance-related conditions, such as polycystic ovary syndrome." (PMID 39769041, 2024). "Chronic hepatic activation of the NF-κB pathway can induce IL-6-mediated insulin resistance; TNF-α inhibition decreases liver fatty acid oxidation and insulin resistance by Kupffer cell activation." (PMID 38672744, 2024). "Insulin resistance of HepG2 hepatocytes was induced in two ways: by preincubating them with the proinflammatory cytokine TNF and with oleic acid, which in both cases resulted in a decrease in [14C]-deoxy-D-glucose transport." (PMID 38399444, 2024). "NF-κB translocation promotes the transcription of additional pro-inflammatory mediators, including IL-1β, IL-6, IL-8, and more TNF-α, further exacerbating insulin resistance." (PMID 39201652, 2024). "TNF-α stimulates IL-1b and IL-6 and increases insulin resistance by phosphorylating insulin receptors." (PMID 39597886, 2024). "ADAM17 (TACE-TNF-α converting enzyme) is the enzyme responsible for the conversion of TNF-α, and its high expression is correlated with insulin resistance development." (PMID 39273582, 2024). "Vanadium effectively reversed hepatocyte insulin resistance, induced by TNF, and the VO-OHpic vanadium complex’s mechanism of reversing insulin resistance was related to the inhibition of the dual specificity phosphatase, PTEN." (PMID 38399444, 2024). "An elevated level of TNFα inhibits tyrosine kinase activity and results in insulin resistance, which has an impact on worsening metabolic homeostasis (diabetes and dyslipidaemia) and, consequently, worse IBD symptoms." (PMID 39335613, 2024). "Firstly, as an active endocrine organ, VAT releases a plethora of inflammatory cytokines such as IL-6 and TNF-α, thereby inducing a low-grade inflammatory state and insulin resistance." (PMID 38685072, 2024).
Insulin resistance (continued). "TNF-α is a potent activator of NF-κB, which induces insulin resistance through serine phosphorylation of the insulin receptor substrate-1 (IRS1)." (PMID 38164478, 2024). "This nice publication identified Nox3 as sole ROS source in TNF–stimulated HepG2 cells, the JNK-pathway as ROS-mediated target, the involvement of ROS in cellular insulin resistance and a possible interplay of TNF, PKC and p47phox-mediated activation of Nox3." (PMID 38397817, 2024). "Leptin-1 also increased serum adiponectin and decreased serum TNF-α and IL-6 level signifying the improvement in insulin-sensitivity and decrease in insulin-resistance, respectively in db/db mice." (PMID 39490585, 2024). "The key compounds target multiple core proteins and modulate various pathways including metabolic pathways, IL-17, NF-κB, TNF, cAMP, insulin resistance, and AGE-RAGE signaling." (PMID 39458839, 2024). "Building upon these findings, the present study aims to additional elucidate the role of CXCR1/2 signaling in IR using TNF-a induced insulin resistance in vitro models." (PMID 39627194, 2024). "Excessive adipose tissue produces a number of proinflammatory cytokines, such as TNF-α, IL-6, and IL-1β, promoting local and systemic chronic low-grade inflammation and resulting in insulin resistance." (PMID 39125786, 2024). "The representative adipokines secreted from adipose tissues with an increased plasma leptin, resistin, and TNF-α, and a reduced plasma adiponectin are related to systemic insulin resistance." (PMID 39065815, 2024). "TNF-α is involved in insulin resistance by activating inflammatory kinases, including c-Jun N-terminal kinase (JNK) and inhibitor kappa B kinase (IKK)." (PMID 38750502, 2024). "In rats with pancreatic disorder and dexamethasone-induced insulin resistance, crocetin reduced free fatty acids, triglyceride, and TNF-α, and increased insulin secretion by reinforcing pancreatic islet beta cells." (PMID 38419885, 2024). "Pro-inflammatory cytokines showed a correlation with insulin resistance in adipocytes, especially TNF-α, a major mediator in the development of chronic inflammation that leads to a reduction in insulin-induced glucose uptake ability." (PMID 38543073, 2024). "These M1 macrophages enhance the production of proinflammatory cytokines (such as IL-6, IL-12, and TNF-α), which impede the insulin action on adipocytes, linking inflammation with insulin resistance." (PMID 39273520, 2024). "The immune-inflammatory mediators, such as TNF-α, IL-1, and IL-6, can lead to insulin resistance due to oxidative stress from high glucose intake, reduce insulin sensitivity, and produce high levels of these mediators in the bloodstream." (PMID 39199338, 2024). "Our first aim was to confirm the use of TNF-α and hypoxia to induce acute insulin resistance and inflammation in differentiated 3T3-L1 adipocytes and examine cell viability in the model." (PMID 39415617, 2024). "As adipocytes expand, immune cells, particularly macrophages, infiltrate the adipose tissue and secrete pro-inflammatory cytokines such as TNF-α and IL-6, which play a key role in the development of insulin resistance." (PMID 39700087, 2024). "TNF-α plays a pivotal role in the development of insulin resistance by reducing the expression of the insulin-regulated glucose transporter type 4 (GLUT4) in adipocytes and skeletal muscle." (PMID 39519203, 2024). "This TNF has also been shown to have a direct impact on diabetes by playing an important role in the development of insulin resistance." (PMID 38920850, 2024). "By reducing MDA and TNF-α, the worsening of pancreatic cell damage and insulin resistance can be decelerated, and the disease progression and its complication will be slowed down." (PMID 38266537, 2024). "When TNF-α is released, it activates redox-sensitive kinases, which can promote proinflammatory pathways and insulin resistance." (PMID 38884676, 2024).
Insulin resistance (continued). "Arecoline can also stimulate the production of pro-inflammatory cytokines, such as TNF-α and IL-6, which are known to lead to insulin resistance and MetS." (PMID 38894993, 2024). "Activated immune cells release cytokines such as TNFα and IL-1β, which activate a series of intracellular signalling pathways, altering insulin signalling and inducing insulin resistance." (PMID 38999869, 2024). "The modulation of inflammatory markers like interleukin-1β (IL-1β), tumor necrosis factor-α (TNF-α), and interleukin-6 (IL-6) is crucial in T2DM, as their elevated levels are associated with disease progression, insulin resistance, and β-cell dysfunction." (PMID 39840100, 2024). "The first mechanism is supported by the report that anti-TNFα treatment ameliorates insulin sensitivity and also by the findings that TNFα-activated JNK directly phosphorylates IRS1/2, causing insulin resistance." (PMID 38397480, 2024). "Under TNF stimulation, they were able to prevent insulin resistance and enhance the expression of GLUT4." (PMID 38672494, 2024). "In particular, an increase in T lymphocytes that secrete IFN-α and TNF-α, which are related to insulin resistance, has been documented." (PMID 38732533, 2024). "Chronic inflammation driven by cytokines (such as IL-17, TNFα, and IL-6) exacerbates insulin resistance, which plays a key role." (PMID 39598018, 2024). "Patients with hyperlipidemia and insulin resistance often exhibit abnormal levels of inflammatory factors, such as IL‐1β and TNF‐α in their adipose tissue and serum compared to healthy individuals." (PMID 39554323, 2024). "TNF-α inhibits peripheral insulin resistance and free fatty acid (FFA) via inducing serine phosphorylation of the insulin receptor 1 substrate-1." (PMID 39149648, 2024). "The novel findings of animal studies demonstrating that TNF-α has a direct role in the pathogenesis of diabetes and insulin resistance have opened the door for new studies in this field." (PMID 38842591, 2024). "First, we observed the effects of mSMG on blood glucose, blood lipids, insulin resistance and TNF-α." (PMID 39285464, 2024). "Several mechanisms have been reviewed regarding the glucose-lowering effects of biologics, including reduced TNFα-induced insulin resistance, reduced soluble ICAM1 levels, and increased high-molecular-weight adiponectin." (PMID 38842591, 2024). "This activation further triggers the production of IL-1β and TNF-α, ultimately resulting in the impairment of insulin signaling and the development of insulin resistance (IR)." (PMID 39564209, 2024). "Increases in inflammatory factors, such as tumor necrosis factor-alpha and interleukin 6, can further exacerbate insulin resistance, promoting thrombosis and atherosclerosis." (PMID 39744244, 2024). "TNF-alpha is an adipokine known to negatively regulate adipogenesis and induce insulin resistance, which suggest that LITAF is an important upstream mediator of adipogenesis." (PMID 38991381, 2024). "Previous studies have shown that TNF-α which is stored in the adipose tissue of obese animals and humans can lead to insulin resistance in obese individuals." (PMID 38164478, 2024). "Significantly elevated levels of cytokines like IL-6 and TNF-α in the adipose tissue highlight an inflammatory milieu that further complicates insulin resistance, endothelial dysfunction, and other metabolic conditions." (PMID 39064298, 2024). "This included those involved in insulin resistance, adherens junctions, metabolic processes, and the IL-17, cAMP, relaxin, TNF signaling pathways as well as the AGE-RAGE signaling pathway in diabetic complications." (PMID 39458839, 2024). "The elevation of pro-inflammatory mediators, such as IL-6 and TNFα, is believed to contribute to the onset of various age-related conditions, including diabetes mellitus and insulin resistance." (PMID 38317257, 2024).